SP1 (Sp1 transcription factor)
Diseases named in the same sentence as SP1 in open-access papers (continued):
Sharing a sentence is not in itself a finding about the gene and the disease.
tumor (continued). "Indeed, the average numbers of tumor spheres in HepG2 cells pretreated with sh-Sp1-4 were significantly decreased than those in control and WT cells, which were 4.0±0.8, 6.3±0.5, 6.8±0.7, correspondingly (P<0.05)." (PMID 27685621, 2016). "Sp1 is upregulated in several tumor tissues, suggesting a role in tumor maintenance." (PMID 25738304, 2015). "Therefore, TRIM22 has the potential to inhibit the transcription of several host genes driven by Sp1 and to suppress cellular or even tumor growth." (PMID 26683615, 2015). "Finally, a recent study demonstrated that Sp1 level accumulated strongly in early stage of lung tumor formation, and that Sp1 expression is maintained at intermediate levels when tumor cells become invasive or malignant." (PMID 25738304, 2015). "The findings also substantiate the dominant role of Sp1 in driving AR expression and thus reinforce the rationale of targeting this transcription factor, as this action will promote binding of competing pur-α and inhibit tumour progression." (PMID 26448047, 2015). "To further examine whether miR-200b exerts its tumour suppressor function through dysregulation of Sp1, we performed functional analyses on Sp1." (PMID 25639535, 2015). "Since down-regulation of Sp-1 leads to inhibition of cell proliferation, transactivation gene expression might be a possible mechanism for preventing the tumour cell invasion and metastasis." (PMID 25639535, 2015). "Accordingly, Sp1 inhibition may decrease tumor formation, growth and metastasis, representing an attractive target, despite being considered undruggable by conventional drug discovery approaches." (PMID 26536461, 2015). "Targeting SP1 has been reported to have anti-tumor properties." (PMID 26362062, 2015). "It was reported that SP1 is upregulated in multiple tumors and correlate with tumor progression." (PMID 26177288, 2015). "It is of great value to explore the mechanism of ETS and SP1 modulation during tumor progression." (PMID 26177288, 2015). "Recently, accumulating experimental evidence suggests that Sp1 may be involved in inducible gene expression in response to hypoxia, thus contributing to tumor biology." (PMID 26703734, 2015). "In addition to SP1, tumor supporters such as E2F3a, BAX, BMI-1, DCX and Reelin are also targeted by miR-128." (PMID 24959930, 2014). "Targeting Sp1 expression may reduce KIF14 levels in tumor cells, and could contribute to a therapeutic strategy against OvCa progression." (PMID 24626475, 2014). "SP1 is a transcription factor that regulates gene expression and may promote tumor progression and lead to bad outcome for patients as observed in our data." (PMID 24894543, 2014). "The results showed that a single CpG site at −155 bp, located at the junction of the two Sp1/Sp3 binding sites, was more significantly methylated in tumor tissues (40.4% and 9.0%, respectively), in which CMTM3 was down-regulated, than in corresponding non-tumor tissues." (PMID 24586462, 2014). "Therefore, the role of Sp1 in tumor development is paradox and variable, largely depending on the cellular context." (PMID 25099028, 2014). "Deregulation of Sp1 may promote tumor development through regulating transcription of genes, such as c-Myc, cyclin D1, VEGF and MMP9." (PMID 25099028, 2014). "SP1 has a wide variety of functions that favor generation of neoplasms." (PMID 24959930, 2014). "Sp1, too, could act as a Tgfβ-dependent tumor suppressor, by controlling Ink4b or Arf (this work), or as an oncogene by facilitating EMT." (PMID 23940569, 2013). "Our data raise the possibility that CUR may prevent metastasis ability of CRC cells in vitro and in vivo through inhibition of Sp-1 and its housekeeping gene expressions which are known to be involved in tumor progression." (PMID 23970932, 2013). "Notably, naturally occurring compounds, such as curcumin and betulinic acid, have been reported to suppress tumor growth via the downregulation of Sp1 expression in prostate and bladder cancer cells." (PMID 23403540, 2013).
tumor (continued). "Interestingly, we found that vemurafenib treatment in mice bearing drug-resistant A375 xenografts also induced increased FDG tumor uptake, accompanied by increases in Hif-1α, Sp1 and Ksr protein levels." (PMID 22651703, 2012). "Finally, a growing number of compounds inhibit Sp1 and suppress tumor formation, but a detailed mechanism and the side effects require further clarification." (PMID 23148884, 2012). "Finally, we confirmed that over-expression of Sp1 inhibited the endogenous USP22 expression in human tumor cells." (PMID 23300749, 2012). "Although Sp1 deregulation might be beneficial for tumour cells, its overexpression induces apoptosis of untransformed cells." (PMID 19753117, 2009). "Knowing that ADAM17 contributes to the invasiveness of tumor cells and that Sp1 binds to its promoter region, it is possible that Sp1 transcription factor may be a new target for anti-invasive therapies." (PMID 19772640, 2009). "Sp1 protein expression has been reported to increase in tumor cells under hypoxic conditions." (PMID 19772640, 2009). "Moreover, betulinic acid, a natural product with anti-tumour activity, induces apoptosis by degrading Sp1 and Sp3." (PMID 19212434, 2009). "Additionally, we tested the effect of Sp1 suppression in tumor cell invasion and migration, using Matrigel basement membrane invasion chambers, a scratch wound-healing assay, and small interfering RNA." (PMID 19772640, 2009). "Sp1 expression levels show a dramatic increase during transformation and this could play a critical role for tumour development or maintenance." (PMID 19753117, 2009). "In addition, we examined the function of Sp1 in tumor invasiveness under normoxic and hypoxic conditions." (PMID 19772640, 2009). "Moreover, down-regulation of over-expressed Sp1 protein in human fibrosarcoma cell lines inhibits tumour formation." (PMID 19212434, 2009). "Although Sp1 deregulation might be beneficial for tumour cells, we and others have previously shown that deregulation of Sp1 expression on its own induces apoptosis of several untransformed cell lines." (PMID 19753117, 2009). "To test if Sp1 contributes to the invasion of tumor cells, we used an in vitro invasion assay." (PMID 19772640, 2009). "However, dysregulation of Sp1 can lead to abnormal cell cycle progression and tumor development." (PMID 40869407, 2025). "Sp1 activates the angiogenic pathway through regulating the vascular endothelial growth factor, platelet reactive protein 1, platelet-derived growth factor, urokinase plasminogen activator, and anti-angiogenic genes to meet the nutritional and oxygen requirements of tumor growth." (PMID 39228402, 2024). "The mRNA level of Sp1 in EC tissues was decreased compared with that in normal tissues (p < 0.001), and low expression of Sp1 was significantly correlated with a clinical stage of IV, a tumor invasion depth of ≥50%, and specific histological types such as endometrioid and mixed (all p < 0.05)." (PMID 38466034, 2024). "The overexpression of SP1 could promote tumor growth compared to the Vector + shNC." (PMID 38368381, 2024). "Our finding that the ELK4‐SP1/3 complex cooperatively regulates gene expression to promote CRC tumor growth raises the intriguing possibility that the combination of a MEK/ERK inhibitor with an SP1 inhibitor might lead to a synergistic inhibitory effect on CRC growth." (PMID 37786278, 2023). "Consequently, we determined whether endothelial Sp1/Sp3 deletion alters tumor angiogenesis and tumor growth." (PMID 36759621, 2023). "Likewise, the silencing or inhibition of Sp1 reduces tumor formation, growth, and metastasis." (PMID 36520928, 2022).
tumor (continued). "Mechanistically, tumor cell-derived granulocyte-macrophage colony stimulating factor (GM-CSF) increased the expression of FcγRIIB on hematopoietic progenitor cells (HPCs) by activating specificity protein 1 (Sp1), subsequently FcγRIIB promoted the generation of MDSCs from HPCs via Stat3 signaling." (PMID 34976216, 2022). "In addition, sh-circRNA induced-tumor inhibition was restored upon Sp1 overexpression." (PMID 33472586, 2021). "However, the equilibrium may be shifted in tumors by tumor-related stimuli, thus giving rise to elevated levels and activity of SP1 and low levels of miR-320a expression, eventually promoting malignancy." (PMID 33731131, 2021). "Therefore, lowering Sp1 levels is a good strategy to prevent tumor cell growth." (PMID 34531430, 2021). "However, it is unclear whether there is a specific interaction between HIF-1α and SP1 promoter in tumor cells." (PMID 31892989, 2020). "In addition, the visible tendency for methylation increases at positions 88 to 103 in the peripheral tumor leukocytes (PTLs) at 28 dpi could implicate the importance of the Sp1 site and/or CCAAT box in vTR expression during tumorigenesis." (PMID 32967954, 2020). "In addition, the western blot data of PC-3-transplanted tumor tissues demonstrated that the protein levels of Sp1, Sp3/4, Survivin, and Cyclin D1 were decreased, while the protein levels of c-Caspase 3 and c-PARP-1 were increased in the HD and PC groups (compared with the NC and LD groups)." (PMID 32851058, 2020). "We just suspect that SP1 may change its transcriptional activity at different tumor stages." (PMID 31892989, 2020). "Studies of HIF-1α and SP1 in tumor metastasis are rare and related mechanisms remain unclear." (PMID 31892989, 2020). "Thus, Sp1 has a putative job in cell cycle regulation which may result into tumor development and progression upon disruption." (PMID 32050495, 2020). "The abnormal activation of Sp1 could up-regulate the expression of tumor related factors and angiogenic factors, thus providing a good microenvironment for tumor growth, and promoting the proliferation, metastasis and angiogenesis of colon, gastric and pancreatic tumors and regulate apoptosis." (PMID 33187481, 2020). "Therefore, downregulating Sp1 is a good strategy for preventing tumor cell growth." (PMID 28225083, 2017). "Furthermore, previous studies have indicated that Sp1 might extend tumor growth and metastasis through the overexpression of many Sp1 target downstream genes, including mesenchymal factors, genes that promote cell proliferation, and oncogenes." (PMID 26763486, 2016). "Also, JWA suppresses tumor angiogenesis via Sp1-activated MMP-2 in human gastric cancer." (PMID 26046674, 2015). "On the basis of these findings, it appears that the inactivation of ARNT or its partners, such as Sp1 and AhR, inhibits tumor growth; however, it may also promote metastasis, allowing tumor cells to escape from their immediate environment, such as during targeted therapy." (PMID 25839165, 2015). "Hence, our work provided a clue that, whether it may prevent tumour formation, proliferation, migration and invasion by inhibiting the expressions of Sp1′s housekeeping genes." (PMID 25639535, 2015). "Therefore, Sp1 may serve as an oncogene or a tumor suppressor in tumor development and deserved to be studied in depth." (PMID 25099028, 2014). "Hence, inhibition of Sp-1 and its housekeeping gene expressions is an important hypothesis to prevents tumor formation, migration, and invasion." (PMID 23970932, 2013).
tumor (continued). "It was reported that Sp-1 mediates the transforming growth factor-β (TNF-β) stimulated EMT and cell migration, and also downregulates E-cad and upregulation of MMP-9, thereby loss of cell-cell contact resulting in EMT, which in turn results in tumor cell invasion and metastasis." (PMID 23970932, 2013). "Sp1, an important mediator of the cell cycle, may activate IL-10 in response to inflammatory signals and play a role in the cellular responses to DNA damage and tumor metastasis." (PMID 21457566, 2011). "Importantly, Sp1 expression is increased in a number of tumour cells and this could be a critical factor for tumour development or maintenance." (PMID 19753117, 2009). "Furthermore, suppression of Sp1 decreases invasiveness and migration in U87 tumor cells." (PMID 19772640, 2009). "Here, we found that serum-stimulated PKCζ further enhanced the interaction of SP1 with TEAD4, which is in agreement with the activation of YAP/TEAD transcriptional activity upon serum stimulation to sustain tumor cell proliferation and survival." (PMID 39875519, 2025). "We found that: 1) SP1 is overexpressed in both PanIN and PDAC tissues; 2) SP1 promotes tumorigenesis in the KPC model; 3) SP1 promotes tumor growth in PDAC cell lines and patient‐derived organoids." (PMID 40832790, 2025). "In GBM cells, Sp-1 likely regulates the AKT signaling axis, enhancing aerobic glycolysis or promoting angiogenesis, thereby affecting tumor cell proliferation, invasion, and migration." (PMID 40471367, 2025). "Specifically, SP1 is known to regulate genes involved in cell cycle progression and DNA repair, while MYC promotes tumor survival through metabolic reprogramming." (PMID 40817807, 2025). "The identification of central TFs such as SP1 and MYC, alongside disease‐specific miRNAs like miR‐21 and miR‐34a, underscores the potential of targeting these regulators to disrupt tumor‐promoting pathways." (PMID 40817807, 2025). "SP1 promotes cell proliferation by shortening the 3′UTR through APA, which is a common phenomenon in tumor cells." (PMID 40290118, 2025). "This comprehensive analysis highlights the intricate role of H3K9ac, SP1, and MGMT in GBM subtypes, particularly in the context of tumor recurrence and TMZ resistance." (PMID 38448295, 2024). "The aim of the study was to evaluate promoter methylation of CDKN1, CDKN2A, MYC, Smad3, SP1, and UBC genes in tumor tissue of HNSCC patients." (PMID 38540340, 2024). "The modulation of histone modifications serves to enhance the binding capacity of the transcription factor Sp1 to the Gpr160 gene promoter, consequently increasing GPR160 expression following tumor infiltration." (PMID 39448865, 2024). "CEBPB and Sp1 can potentially regulate CCL28, while only CEBPB was highly expressed in hypoxic tumor cells." (PMID 39075504, 2024). "The aim of the study was to investigate the methylation status of CDKN1, CDKN2A, MYC, Smad3, SP1, and UBC genes in tumor tissue (control-normal tissue) in 50 patients (37 men and 13 women) with HPV-negative HNSCC." (PMID 38540340, 2024). "Our study revealed that the expression levels of NAV1, EHMT2, SP1, SLC6A4, OPRD1, and CYP3A4 between the normal and tumor were statistically significant." (PMID 38352696, 2024). "ELK4 cooperates with SP1 and SP3 instead of SRF to transcriptionally regulate LRG1, among others, to promote tumor angiogenesis, tumor growth, and metastasis." (PMID 37786278, 2023). "The “Correlation Analysis” module of the GEPIA2 data platform was used to analyze the correlation between Sp1 and DNA-PKcs (parameters set as Gene: Sp1/DNA-PKcs; Correlation Coefficient: Pearson; TCGA Tumor: CESC Tumor)." (PMID 37445835, 2023). "Of note, we also observed a positive correlation between the tumor vasculature marker CD31 and the protein levels of LRG1, ELK4, SP1 and SP3 in our CRC cohort." (PMID 37786278, 2023).
tumor (continued). "According to the research on non-small cell lung cancer, PM2.5 upregulated the expression of DLAT to promote glycolysis through the dual regulation mechanism of Sp1-DLAT and eIF4E-DLAT axis, enhancing the proliferation of tumor cells." (PMID 36925927, 2023). "Sp1 transcription factor (SP1), initially identified as a transcription factor, plays a crucial role in normal biological processes, neoplastic development, and tumor migration." (PMID 37311884, 2023). "There is also a documented relationship between Sp1 and the upregulation of MMP9, a previously highlighted gene involved with tumor invasion and metastasis." (PMID 37373974, 2023). "But also, TFP/TMX targets the transcription factor Sp1 (specificity protein-1) acting on the DR5 gene increasing the expression of this receptor, allowing both processes efficient apoptotic cell death of the tumor cells." (PMID 38136610, 2023). "Sp1 is overexpressed in some tumours and often interacts with the PI3K/AKT signalling pathway and other transcription factors to regulate tumour glycolysis." (PMID 35568711, 2022). "Among the NAC-induced miRNAs in non-responders is miR-539-5p, which has been shown to act as a tumor suppressor in BC by targeting EGFR, LAMA4, and SP1 thus leading to the inhibition of proliferation and migration of BC cells." (PMID 36387168, 2022). "Fyn and specificity protein 1 (SP1) played a significant role in the reduced expression of SATB1 and tumor progression in CRC following PRNP knockdown." (PMID 36359353, 2022). "These HNSC tumor tissues were collected from patients across North Carolina as part of our CHANCE study and assigned to categories (e.g., DP, SP1, SP2, or DN) according to the clinical assay results." (PMID 36148399, 2022). "Betulinic acid downregulated Sp1, Sp3, Sp4 and EZH2 in tumor tissues and this was accompanied by simultaneous decrease in the levels of miR20a, miR-106a and miR-106b." (PMID 36615262, 2022). "Taken together, the present study demonstrates that the histone modifier KDM3A epigenetically activates SP1 transcription, which further activates the glycolysis-related PFKFB4 in OS, consequently leading to tumor cell growth and metastasis." (PMID 35590288, 2022). "And miR‐383‐5p, a posttranscriptional regulator discovered in our previous research as a tumor suppressor in HCC, was predicted as a potential bridge that mediates the regulation of E2F7 on SP1." (PMID 35924788, 2022). "All of them not only can be upregulated by SNA involved in tumor progression but also contain the candidate SNA and EGR/SP1 overlapping regions on their promoter." (PMID 34571852, 2021). "Future studies will seek to identify the mechanism that unleashes SP1 in MLL3 mutant cells and its contribution to aggressive tumor behavior." (PMID 34581028, 2021). "Silencing Sp1 in HDLECs resulted in decreased recruitment of M2-polarized THP-1 macrophages and tumour cells (SiHa), whereas Sp1 overexpression increased cell migration." (PMID 33484377, 2021). "Downregulation of Sp1 suppressed the proliferation, migration, and invasion of MDA–MB-231 and MDA–MB-468 cells as well as tumor growth in vivo." (PMID 34145213, 2021). "Through a series of in vitro assays, we found that miR-92b and Sp1 formed a positive feedback regulatory loop that promoted the migration, invasion and proliferation of HNSCC, and promoted tumor growth in vivo." (PMID 34905435, 2021). "We found that silencing AFAP1-AS1 and Sp1 or upregulating miR-2110 suppressed the proliferation, migration, and invasion of MDA–MB-231 and MDA–MB-468 cells in vitro as well as tumor growth in vivo." (PMID 34145213, 2021). "The results showed that the expression of SP1, KEAP1, AIFM2, and NOX4 all increased in tumor tissues." (PMID 34745421, 2021). "For example, a recent study has proved that SP1 is involved in the PI3K/Akt signaling pathway, thereby contributing to tumor angiogenesis and hepatocellular development." (PMID 34988109, 2021).